MRS2 (magnesium transporter MRS2)
Description:
Magnesium transporter that mediates the influx of magnesium into the mitochondrial matrix and regulates magnesium metabolism. Also permeable to calcium, sodium and potassium ions. Required for normal expression of the mitochondrial respiratory complex I subunits. May play a role in maintaining the inner mitochondrial membrane potential.
Synonyms: HPT; MRS2L
Tractability: Antibody: UniProt predicts a signal peptide or a membrane-spanning region. PROTAC: ubiquitination databases record sites on it; its protein half-life has been measured.
Gene: Protein-coding gene on chromosome 6 (24,402,908 to 24,426,194, forward strand). Ensembl gene ENSG00000124532.
Subcellular location: Mitochondrion inner membrane
Pathways (Reactome):
Transport of small molecules: Miscellaneous transport and binding events
Gene Ontology:
Molecular function: magnesium ion transmembrane transporter activity
Biological process: mitochondrial magnesium ion transmembrane transport; transmembrane transport; lactate metabolic process
Cellular component: mitochondrion; mitochondrial inner membrane
Genetic constraint (gnomAD): Loss-of-function variants: 17 observed, 27.1 expected, observed/expected ratio (o/e) 0.63, 90% interval 0.43 to 0.94. The upper end of that interval is the gene's LOEUF score, 0.94, which puts it in group 3 of 6, group 1 being the genes least tolerant of losing a copy. Missense variants: 319 observed, 347.93 expected, observed/expected ratio (o/e) 0.92, 90% interval 0.84 to 1.01. Synonymous variants: 133 observed, 127.37 expected, observed/expected ratio (o/e) 1.04, 90% interval 0.91 to 1.21.
Homologues: Orthologues: chimpanzee MRS2 (95% identical), macaque MRS2 (93% identical), dog MRS2 (89% identical), guinea pig MRS2 (86% identical), rat Mrs2 (84% identical), mouse Mrs2 (82% identical), rabbit MRS2 (82% identical), pig MRS2 (77% identical), tropical clawed frog mrs2 (66% identical), zebrafish mrs2 (55% identical).
Diseases named in the same sentence as MRS2 in open-access papers:
MRS2 is named in the same sentence as 15 diseases in open-access papers, as found by Europe PMC text mining. Sharing a sentence is not in itself a finding about the gene and the disease. The quoted sentences say what the papers report.
gastric cancer (5 papers, 2019 to 2024). A primary or metastatic malignant neoplasm involving the stomach. "Further, a missense variation at D216 has been identified associated with malignant melanoma and MRS2 expression and activity is implicated in gastric cancer." (PMID 38989547, 2024). "Further, MRS2 is upregulated in multidrug resistant (MDR) gastric cancer (GC) cells, and the higher MRS2 activity is linked with increased resistance to apoptosis." (PMID 38989547, 2024). "Mg, crucial in all the metabolic pathways, is mainly stored within the mitochondria and Mrs2, a mitochondrial Mg transporter, is upregulated in a multidrug-resistant gastric cancer cell line." (PMID 31461915, 2019). "In gastric cancer cells, Mrs2 overexpression inhibits adriamycin-induced apoptosis, probably by suppressing Bax-induced cytochrome-C release by mitochondria." (PMID 30884858, 2019). "The up-regulation of MRS2 has also been identified in a gastric cancer cell line with a multidrug-resistant phenotype, and it may exert its effect via regulating cell cycles and releasing cytochrome C." (PMID 36835443, 2023). "Interestingly, Mrs2 expression seems positively correlated with the multidrug resistance of gastric cancer cells in vitro and in vivo." (PMID 30884858, 2019). "Moreover, p27 is downregulated while cyclin D1 is upregulated following Mrs2 overexpression, leading to gastric cancer cell proliferation enhancement." (PMID 30884858, 2019). "It has also been shown that human mitochondrial Mrs2 protein expression is upregulated in a multidrug-resistant gastric cancer cell line compared to its non-resistant counterpart." (PMID 30884858, 2019). "Although these data suggest that Mrs2 may be a promising target against multidrug resistant gastric cancer, the role of mitochondrial Mg2+ has not been yet elucidated." (PMID 30884858, 2019).
gastric adenocarcinoma (2 papers, 2013 to 2016). "On the contrary, an upregulation of Mrs2 has been observed in parental human gastric adenocarcinoma cell lines, indicating that high expression of Mrs2 may protect against death." (PMID 27289382, 2016). "A subtractive hybridization method applied on vincristine or adriamycin resistant and parental human gastric adenocarcinoma cell lines highlighted upregulation of Mrs2, suggesting that high expression of Mrs2 may protect against death." (PMID 24027528, 2013).
glioma (2 papers, 2020 to 2022). A benign or malignant brain and spinal cord tumor that arises from glial cells (astrocytes, oligodendrocytes, ependymal cells). "The results showed that glioma tissues have higher expression of LDHA, HLF1A, SLC16A1, and MRS2 and lower expression of LDHB and SLC25A12 compared with paracancerous tissues." (PMID 36698888, 2022).
colitis (1 paper, 2023). Inflammation of the colon. "In our lipidomic studies, we analyzed the kinetic profiles of some putative pro-resolving metabolites, such as neuroprotectins (NPD-1, NPDx), maresin-2 (Mrs-2) and resolvin-D5, during the time course of DSS-induced colitis." (PMID 37446212, 2023).
endometrial cancer (1 paper, 2026). Primary or metastatic malignant neoplasm involving the endometrium (mucous membrane that lines the endometrial cavity). "Additionally, three genes—MRPL15, MTFR2, and MTHFD2—were found functionally linked to MRS2, and their upregulation is associated with unfavorable outcomes in endometrial cancer patients." (PMID 41551444, 2026). "Given that MRS2 regulates mitochondrial function in lactate-rich microenvironments, we hypothesize that it may play a critical regulatory role in energy metabolism-associated cancers such as endometrial cancer." (PMID 41551444, 2026). "Analysis of TCGA data revealed significant upregulation of MRS2 in 21 tumor types, including endometrial cancer." (PMID 41551444, 2026). "MRS2 was upregulated across tumor tissues; in endometrial cancer, there was a significant difference in its expression between cancerous tissues and normal tissues." (PMID 41551444, 2026). "This study demonstrated that MRS2 is overexpressed in multiple cancers, especially in endometrial cancer, where it correlates with poor prognosis and shows diagnostic potential." (PMID 41551444, 2026). "MRS2 and its related genes may serve as key regulatory genes for mitochondrial metabolic abnormalities in endometrial cancer." (PMID 41551444, 2026). "Notably, MRS2 knockdown resulted in reduced proliferation of KLE cells, supporting a potential functional role of MRS2 in endometrial cancer progression." (PMID 41551444, 2026). "This suggests that endometrial cancer patients with high MRS2 expression may exhibit increased sensitivity to this inhibitor." (PMID 41551444, 2026). "Our findings revealed that increased lactate levels in endometrial cancer cells (KLE) after LPS stimulation, along with upregulated MRS2 expression." (PMID 41551444, 2026). "Interestingly, MRS2 knockdown did not significantly alter lactate levels in the cell supernatant, suggesting that LPS—but not MRS2—is the primary inducer of lactate production in endometrial cancer cells, as supported by earlier findings in ‘Lactic acid increases ROS production by activating MRS2’." (PMID 41551444, 2026).
Obesity (1 paper, 2021). Accumulation of substantial excess body fat. "For SAT, the amount of DE mRNAs of obesity was 185 (50 for overweight, 54 for obesity, and 107 for obesity with MS), and only 3 mRNAs (JSRP1, MRS2 and STK40) were shared by all these 3 obesity components as shown in Venn diagram." (PMID 34621242, 2021).
cancer (5 papers, 2016 to 2026). A tumor composed of atypical neoplastic, often pleomorphic cells that invade other tissues. "In the context of human cancers, the dysregulation of magnesium homeostasis and the aberrant expression of magnesium transporters/channels, including MRS2, are associated with key processes of cancer metastasis, such as local invasion, transmigration, and colonization." (PMID 36835443, 2023). "Due to the unique structural location of Mrs2 and its crucial role in subcellular magnesium ion transport and mitochondrial metabolic functions, Mrs2 has a great potential for elucidating the mechanism of action of magnesium ions against cancer." (PMID 39200180, 2024).
tumor (3 papers, 2022 to 2026). "High MRS2 expression correlated with poor tumor differentiation and worse prognosis." (PMID 41551444, 2026). "Therefore, subcellular magnesium ion transport mediated by Mrs2 is likely to become a crucial “switch” in regulating tumor cell growth." (PMID 39200180, 2024). "Mrs2 may serve as a new target for energy metabolism-related tumor therapy." (PMID 39200180, 2024).
MRS2 also shares sentences with these, for which no sentence is quoted: infection (3 papers); Cognitive impairment (1); colon cancer (1); fungal infection (1); Hypertension (1); malignant melanoma (1); neurodegenerative disease (1).